IL6 (interleukin 6)
Diseases named in the same sentence as IL6 in open-access papers (continued):
Sharing a sentence is not in itself a finding about the gene and the disease.
tumor (continued). "In NSCLC sufferers, their serum and tumor samples comprised elevated quantities of STAT3-driven cytokines IL-6/11/22 and leptin and HGF growth factors." (PMID 36497125, 2022). "An experiment in vivo had proved that IL-6 contributed to blood–brain barrier dysfunction via JAK-STAT signaling pathway in tumor microenvironment." (PMID 35799791, 2022). "IL-6 appears to be an important player in UM tumor progression, as increased expression in the level of this cytokine also correlates with an increased tumor prominence and the presence of both macrophage and Treg infiltration of the primary tumor." (PMID 35163491, 2022). "High-fat diet (HFD)-accelerated tumor growth was correlated with the increased M2/M1 ratio and IL-6 expression in the model mice." (PMID 36117852, 2022). "HSP72 and HSP105 on the membrane of TEVs interact with TLR2 and TLR4 on DCs which induced IL-6 secretion by DCs that increased STAT3-dependent MMP-9 transcription activity in cancer cells resulting in tumor invasion." (PMID 36612080, 2022). "R848 delivered by complement C3-targeted liposomes triggered various signal cascades to increase the expression of cytokines and factors (such as TNF-α, IL-1β, IL-6 and IL-12), leading to the delay of tumor growth in 4T1 tumor-bearing mice." (PMID 35413927, 2022). "IL-6 in turn induces autophagy in both tumor microenvironment and distant tissues, recycling nutrients, such as amino acids to facilitate tumor metabolism." (PMID 34459894, 2022). "In contrast to the single-tumor model, the highest IL-6 level was detected in mice treated with isotype control antibodies and was reduced in all active treatment groups." (PMID 35141399, 2022). "Otherwise the immunosuppressive cells suppress the function of CD8+ T cells and NK cells by secreting cytokines such as EGF, TNF-α, CXCL12, IL-10 and IL-6, thereby ensuring the survival of tumor cells." (PMID 35454769, 2022). "Targeted colony stimulating factor (CSF-1), autophagy, NF-KB, Mir-214, IL-6, and toll-like receptors (TLRs) can transform TAMs from a pro-tumor phenotype into an antitumor phenotype (M1)." (PMID 36457492, 2022). "Partially consistent with the Kaplan–Meier analysis, PGE2 and IL-6 were significant predictors of longer survival (P = 0.033 and 0.031, respectively), whereas IL-2 and IL-6 predicted tumor response to c4G12 treatment (P = 0.030 and 0.013, respectively)." (PMID 35665759, 2022). "IPA predicted that a regulatory network involving IL-6 and leading to the invasion of tumour cells was significantly activated." (PMID 35022523, 2022). "PGE1 is known to stimulate angiogenesis, another essential process for continued tumor growth in vivo, and cytokines such as IL-6 and IL-8 have been shown to promote cancer cell invasion." (PMID 35681614, 2022). "Apart from immune cells, tumor cells also secrete various cytokines such as TNF、GM-CSF、IL-6、IFN-γand MCP-1." (PMID 36530985, 2022). "Treatment with combination therapy increased the plasma concentrations of IFN-γ, TNF-α, IL-2, and IL-6, indicating that tumor-infiltrating Treg cells gained CD4 effector function." (PMID 36090972, 2022). "The resulting excessive activity of IL-6 leads to the overexpression of the proto-oncogene c-Myc, multiple pro-inflammatory cytokines and, consequently, tumor growth, tumor progression and drug resistance." (PMID 36611932, 2022). "A similar TLR2/4-STAT3 response driven by HSPs was seen in bone marrow-derived dendritic cells (BMDCs) promoting a pro-tumor IL-6, PGE-2, IL-1, and TNF response after exosome treatment." (PMID 35320943, 2022). "Once differentiated into TAMs, these M2-like cells release IL-6 along with effector cells and tumor cells, thereby promoting tumor plasticity, a term referring to the ability of epithelial cells to transition to mesenchymal phenotypes." (PMID 36031601, 2022). "Accordingly, CAF-derived IL6 increases tumor cell proliferation, epithelial–mesenchymal transition (EMT) and metastasis in PDAC." (PMID 36612058, 2022).
tumor (continued). "A range of cytokines, including TNF, RANKL, IL-1, and IL-6, induce inflammation and promote tumor cell metastatic capacity through altering dissemination and colonization in distant metastatic lesions." (PMID 36090985, 2022). "C1QC+ tumor-associated macrophages and INHBA+ monocytes showed a significant reduction in inflammation-related pathways, including the interferon alpha pathway, IL-6 pathway, and interferon gamma pathway." (PMID 36052088, 2022). "Next, we ascertained if neutrophil-derived IL-1β was contributory to CAF-tumor cell IL-6/STAT-3 signaling." (PMID 36107485, 2022). "IL-6 has been primarily reported as a factor in inflammation, but it is also known to be involved in tumor progression in many cancers." (PMID 35089951, 2022). "For example, IL-6-ablated mice and STAT3-deficient mice exposed to azoxymethane (AOM)/DSS exhibited reduced tumor numbers, size and proliferation." (PMID 36135048, 2022). "In contrast, IL6-/- mice treated only with gDE7 showed a 33% survival rate and 10% remained tumor-free at D60." (PMID 36405719, 2022). "Together, these data reveal a role for neutrophil-derived IL-1β in promoting iCAF polarization and inducing CAF-tumor cell IL-6/STAT3 signaling in the PDAC TME, which is a central mediator of chemoresistance." (PMID 36107485, 2022). "In this context, the influence of IL-6 on the tumor microenvironment is of pivotal importance, too, as it promotes angiogenesis and impairs anti-tumor immunity." (PMID 36230528, 2022). "IL-1 and IL-6 have been shown to have multiple effects on multiple cell types, and these cytokines participate in various stages of tumor formation, invasion and metastasis." (PMID 35634419, 2022). "Mechanistic experiments demonstrated that IL-9 signalling controls IL-6 production by tumour-infiltrating T cells, leading to IL-6-dependent pSTAT3 activation and proliferation of intestinal epithelial cells [IEC]." (PMID 35793807, 2022). "Our current data with the IL6-/- mouse model demonstrated the relevance of 1MT adjuvanticity in boosting DCs in the tumor microenvironment." (PMID 36405719, 2022). "IL-6, an immunosuppressive cytokine, exhibits a positive correlation with sCD40L (activate T lymphocytes), thus allowing tumor growth." (PMID 36015440, 2022). "Similar results have been reported from studies on glioma and BC whereby TA-MSCs-secreted IL-6 increased the number of CSCs in tumor tissue and promoted proliferation and self-renewal of tumor cells through activating the STAT3 signal pathway." (PMID 35842634, 2022). "The tumor- and host-produced cytokines, such as IL-6 and TNF-α, are believed to play a significant role in the catabolism and weight loss associated with some malignant and nonmalignant conditions." (PMID 36471329, 2022). "Results of murine models of NSCLC suggested that the dual blockade of IL-6 and PD-L1 attenuated tumor growth." (PMID 35550592, 2022). "For instance, elevated tumor necrosis factor alpha (TNF-α) and interleukin-6 (IL-6) secretion is known to promote the metastasis and malignancy of tumor cells." (PMID 36555124, 2022). "Tumor production of IL-6 and TGF-β stimulated the differentiation of Th17 cells into CD25high/CD39/CD73 Th17 cells." (PMID 35954312, 2022). "Reduction of S1PR1-STAT3 signaling diminished pro-tumor cytokine production, including IL-6, which resulted in reduced tumor progression in mouse models of bladder cancer and CAC." (PMID 35163211, 2022). "For example, ER stress stimulates a series of inflammatory factors, including IL-23 and IL-6, in macrophages, thereby promoting tumor progression and metastasis through modifying the immune characteristics of tumor cells." (PMID 36120545, 2022). "As an important pathway in bone homeostasis, the RANK/RANK-L/OPG pathway can be abnormally activated by cytokines secreted from tumor cells such as PTHrP, IL-6, and TNF that can promote osteolytic changes." (PMID 36230816, 2022).
tumor (continued). "In vitro studies support these clinically observed correlations, and it has now been established that adipocyte secreted IL-6 promotes migration of ER+ and ER− tumor cells." (PMID 35163731, 2022). "In TME, some tumor cells or tumor-associated cells secrete immunosuppressive factors, including TGF-β, IDO, PGE2, IL-6, and IL-10, which prevent NK cells from performing normal cytotoxic killing function." (PMID 35681736, 2022). "We observed elevated IL-6 levels in the plasma of tumour-bearing mice compared to healthy mice, confirming its overexpression during tumour progression." (PMID 36077801, 2022). "For example, direct stimulation of tumour cells via IL-6 can induce increased proliferation and invasiveness." (PMID 36429126, 2022). "Our results indicate that the combination of Stt + Tcz effectively and synergistically inhibits the IL-6/IL6R/STAT-3 pathway in tumor cells." (PMID 35465350, 2022). "Our data suggested that the knockdown of GPR81 impaired osteolysis and tumor growth partly because of a decrease in the expression of osteolytic cytokines, including IL-6 and IL-11." (PMID 35428832, 2022). "TAMs exhibit either an immunosuppressive M2-like phenotype, increasing production of anti-inflammatory factors IL-10 and TGF-β, or an anti-tumor M1-like phenotype, releasing pro-inflammatory cytokines IL-12, IL-1, IL-6, and TNF-α." (PMID 35236203, 2022). "It has been proposed that differentiation and function of DCs in cancer patients are impaired due to interaction with tumor cells or tumor-derived cytokines, in particular IL-6." (PMID 35965494, 2022). "Immunosuppressive cytokines (such as IL-6 or others) that are produced by surrounding tumor stroma are augmented in the tumor lesions." (PMID 36173644, 2022). "In contrast, other studies have shown that IL-6 activates, proliferates, and increases the survival rates of lymphocytes during the immune response, suggesting a dual face of IL-6 in regulating various signaling pathways in the tumor microenvironment." (PMID 36685193, 2022). "Under these circumstances, stromal-derived IL-6 in the tumor microenvironment would enhance development of resistance to chemotherapy." (PMID 35406728, 2022). "Consistent with this, IL6 concentrations in tumor tissue lysate and serum were increased in the Abx group compared to the NC group, as detected by ELISA." (PMID 35710492, 2022). "To determine the effects of IFN-γ/St.∆ppGpp on tumor inflammatory cytokines, we removed the tumor tissue from CT26 tumor-bearing mice and used qRT-PCR to measure Il-1β, Tnf-α, Tgf-β, Il-6, Il-10, Gm-CSF, and G-CSF." (PMID 36246355, 2022). "IL-6 secreted by tumor cells interacts with MSCs and further enhances their CXCL7 expression, therefore generate a positive feedback loop." (PMID 35251985, 2022). "Neutrophil-derived IL-1β emerged as a novel mediator of stromal inflammation, inducing inflammatory CAF polarization and CAF-tumor cell IL-6/STAT-3 signaling in ex vivo co-cultures." (PMID 36107485, 2022). "Interleukin-6 (IL-6) is one such inflammatory molecule produced by many cell types, including tumor cells." (PMID 36405719, 2022). "Bazedoxifene also reduces TNBC tumor volume suggesting the translational potential of the compound as an IL-6/JAK/STAT3 inhibitor." (PMID 35371975, 2022). "Previous studies have extensively demonstrated the tumor-promoting effects of IL6-mediated STAT3 signaling." (PMID 36612058, 2022). "Among the type I endometrial patients, only the levels of IL-6 among the proinflammatory cytokines were significantly higher in those with larger tumor size, higher nodal involvement, and distant metastases (stage IV)." (PMID 35053431, 2022). "During transwell coculture with tumor organoids, iCAFs were characterized by the expression of IL6, IL11, and LIF." (PMID 36612058, 2022). "Firstly, TAM-secreted IL-6 promotes epithelial–mesenchymal transition (EMT) in cancer cells to induce their shedding from the primary tumour." (PMID 35020853, 2022).
tumor (continued). "Importantly, the tumor microenvironment is comprised of a myriad of cell types, such as tumor-associated macrophages (TAMs), helper T cells, bone marrow-derived cells, adipocytes, fibroblasts, and cancer cells which secrete pro-inflammatory cytokines, such as IL-6." (PMID 35371975, 2022). "For instance, the proinflammatory cytokine IL-6 controls the proliferation and survival of tumor cells by activating Notch-3 and upregulating the hypoxia response protein, carbonic anhydrase IX." (PMID 36298592, 2022). "Within the tumor microenvironment CAFs are considered a major source of IL6, driving CCA growth in a paracrine manner." (PMID 35619118, 2022). "In breast cancer, CAFs express pro-inflammatory cytokines such as interleukin 6 and 8 to promote tumour cell proliferation and survival." (PMID 35160252, 2022). "Accordingly, use of ruxolitinib or depletion of STAT3 led to regression of tumor growth in vivo, suggesting that IL-6 or possibility other inducers of JAK:STAT signaling are clearly at play during in vivo acquisition of drug resistance." (PMID 35729402, 2022). "IL-6 signaling mediated by tumor-associated macrophages was found to promote a cancer stem cell phenotype in HCC, which due to the self-renewal and tumor-initiating capacity of stem cells, is involved in recurrence and metastasis." (PMID 35814741, 2022). "This change was also evidenced by the significant decreases in IL-6 and Arginase-1 which confirm a shift away from pro-tumor immune phenotypes." (PMID 35513776, 2022). "It was reported that proinflammatory cytokines TNF-α, IL-6, and IL-1β are crucial to immune response, inflammatory, and hematopoiesis, as well as development and progression of tumor." (PMID 35210942, 2022). "CAFs in TME can produce tumor-associated cytokines, such as IL-6, NF-κB, and TGF-β2, which support their function by enhancing secretion of HIF-1α and forming a feedback loop facilitating tumor migration and invasion by shaping the immunosuppressive TME." (PMID 35794625, 2022). "IL-6/STAT3 signaling shows significant enhancement in tumor tissue in human gastric cancer datasets." (PMID 35757757, 2022). "M1 macrophages, through the release of proinflammatory cytokines IL-23, IL-17, and IL-6, can drive tumor growth." (PMID 36140470, 2022). "Mechanistically, we find that FAK regulates interleukin-6, which can act in concert with interleukin-4 secreted by CD4 T-cells to drive elevated expression of PD-L2 on tumour-associated macrophages, dendritic cells and endothelial cells." (PMID 36138073, 2022). "Here we saw a considerable reduction in tumor development when the IL-6-/- mice were immunized with gDE7." (PMID 36405719, 2022). "IL-6-/- tumor-bearing mice were immunized with gDE7 and treated with IDO inhibitors following the “every other day” regimen." (PMID 36405719, 2022). "Our previous work demonstrated that salivary IL-6 is a highly sensitive biomarker of OSCC; thus, we find it significant that both IL-6 and miR-31 are known to contribute to cancer stem cell maintenance in different tumor types." (PMID 35215172, 2022). "Estrogen also appears to weigh the tumour immune balance towards tumour-promoting cytokines (IL-6, IL-4, TNF and IL-17A), M2 (pro-tumour) macrophage polarisation and diminished functional capacities of anti-tumour NK and CD8+ T cells." (PMID 36347875, 2022). "In comparison to the gDE7-treated group, IL-6-/- mice vaccinated with gDE7 and treated with D-1MT or DL-1MT showed significantly decreased tumor mass." (PMID 36405719, 2022). "The C3A and C5A trigger inflammatory response which is crucial step in tumor onset and progression by activating leukocytes, releasing histamine, and stimulating generation of inflammatory mediators such as IL-1, IL-6, IL-1β, IFNγ, and TNF-α." (PMID 36091114, 2022). "Eotaxin, IL-6, and IL-18 levels were lower in the Chemo+Fish Oil group when compared with the Chemotherapy (eotaxin/IL-6) or Tumor (IL-18) groups, respectively (p < 0.05)." (PMID 36428795, 2022).
tumor (continued). "These cytokines are expressed in an altered manner; IL-1β, TNF-α, IL6, IL10, IFN-γ, and CX3CL1 are overexpressed and are correlated with the onset of pain, as it was discovered that they are linked to tumor progression and aggressiveness." (PMID 35054779, 2022). "Based on our results, AM9928 inhibited the secretion of tumor-inflammatory molecules IL-6 and IL-8 and the angiogenic factor VEGF-A in MDA-MB-231 cells and MDA-MB-BrM2 cells as well as the murine GFP-4T1-BrM5 cells." (PMID 35351947, 2022). "The IL6-STAT3 signaling pathway is essential in the inflammatory response of tumor tissues, and the IL6- STAT3 signaling pathway has been reported to promote the enrichment of PCSCs in PCa tissues treated with ADT." (PMID 35292057, 2022). "The selective targeting of oncogenic signaling molecules and the tumor immune microenvironment molecules (i.e., PD1/PD-L1/cytotoxic T lymphocyte associated antigen-4, CTLA-4/NKp-46/CD16/CD28/CD80/IL-2/IL-6) were evaluated." (PMID 36547898, 2022). "Overexpressed IL-6 level was positively correlated with poor liver function, tumor progression, clinical severity, and 6-month mortality." (PMID 36324154, 2022). "Activation of the TLR4 signaling pathway on microglia promotes the secretion of IL-6, and IL-6 can support GSC in regulating tumor growth." (PMID 35740975, 2022). "Direct contact between astrocytes and tumor cells can also promote the secretion of IL-6 and IL-8 by tumor cells." (PMID 36338717, 2022). "In various tumor stem cells, IL-6 is highly expressed by the NF-κB signaling pathway which is triggered by growth factors such as TNF-α and IL-1β." (PMID 36359888, 2022). "The secretome of MSCs is variable but mostly CCL2, CCL5, IL-6, TGFβ, VEGF which have been implicated in tumor growth and/or metastasis are commonly expressed." (PMID 35150338, 2022). "Deep tumor tissue, where the immune response is exhausted and tumor growth is fostered, also has enhanced IL-6/STAT3 signaling, suggesting that this pathway favors carcinogenesis." (PMID 35757757, 2022). "Representative IHC images showed that high levels of IL-6 in tumor samples remarkably correlated with PD-L1 expression and infiltration of M2 macrophages, MDSCs, and Treg cells, but negatively associated with infiltration of CD8+ T cells." (PMID 35550592, 2022). "Meanwhile, the inflammatory cytokines (TNF-α, IFN-γ, and IL-6) in heart, liver, lung, or kidney exhibited significant increase after aPD-L1 treatment in 4T1 tumor-bearing mice relative to that of the saline or HPNP treatments." (PMID 35710545, 2022). "IL-6 can also attract TANs to the tumor environment and can attenuate and reverse the pro-inflammatory effects of neutrophils in the tumor microenvironment thus leading to immune-killing resistance." (PMID 36225938, 2022). "In line with the previous results, qRT-PCR revealed an elevated expression of Il6, Infy, Il1ß and Il12 in the tumor tissue of the DEN/CCl4-treated Cxcl10−/− mice in comparison to the DEN/CCl4-treated WT mice." (PMID 35897689, 2022). "Rodent tumor models shown evidence that increased production of systemic inflammatory cytokines such as TNF-α, IL-1, and IL-6 was associated development of cancer cachexia and weight loss." (PMID 35538112, 2022). "Available data particularly highlight STAT3 activation in neoplastic cell elements consequent to local IL-6 effects as a key determinant of tumor progression and metastasis." (PMID 35406728, 2022). "Consistently, THP-1 macrophages treated with CM of tumor cells or CM of olaparib-treated tumor cells showed significantly up-regulated IL6, IL1B and CXCL1 gene expression." (PMID 35641483, 2022). "M2 TAMs secrete pro-tumor factors (such as IL-4, IL-6, IL-10, IL-13, EGF, and VEGF), while the tumor suppressor M1 TAMs expresses anti-tumor factors (such as IL-12, the major histocompatibility complex (MHC) class II, and TNF-α)." (PMID 36358823, 2022).